PGR (progesterone receptor)
Diseases named in the same sentence as PGR in open-access papers (continued):
Sharing a sentence is not in itself a finding about the gene and the disease.
breast cancer (continued). "According to estrogen receptor (ER), progesterone receptor (PR), and human epidermal growth factor receptor 2 (HER-2) status, breast cancer can be classified into four categories." (PMID 30930932, 2019). "Among the subtypes of breast cancer, TNBC is the most aggressive, lacks the expression of estrogen receptor (ER), progesterone receptor (PR), and human epidermal growth factor receptor 2 (HER2), and accounts for 12–18% of all cases of breast cancer." (PMID 31216782, 2019). "For example, the study on the breast cancer cell line exposed MCF7 (an estrogen and progesterone receptor positive cell line) to Rg3 and the heated extract of ginseng, containing about 5% Rg3." (PMID 31374984, 2019). "Progesterone receptor and HER2 are two other important prognostic-related and predictive genes for breast cancer." (PMID 31921624, 2019). "Triple-negative breast cancer (TNBC), defined as a subtype expressing less estrogen receptor (ER), progesterone receptor (PgR), and human epithelial growth factor receptor (HER2) by immunohistochemistry, accounts for approximately 15% of all breast cancer." (PMID 31461932, 2019). "For example, ER, progesterone receptor (PR), HER2 protein levels, and HER2 genomic amplification are important markers that are predictive and prognostic of breast cancer." (PMID 30754661, 2019). "However, the present studies demonstrate that OCT4 exerts dual effects in breast cancer, which may be related to the multiple intrinsic genes involved in different breast cancer subtypes, especially estrogen receptor (ER), progesterone receptor (PR) and human epidermal growth factor 2 (HER2)." (PMID 31012189, 2019). "The simplest molecular phenotypes are defined by single marker genes, like the estrogen receptor (ER), progesterone receptor (PR), or human epidermal growth factor receptor 2 (HER2/ERBB2) status of breast carcinomas." (PMID 31562358, 2019). "In the clinic, breast cancer is classified according to the presence of three nuclear receptors: human epidermal growth factor receptor 2 (HER2), estrogen receptor (ER) and progesterone receptor (PgR)." (PMID 30483257, 2018). "Breast cancer subtypes are most commonly classified based on the expression of the Estrogen Receptor (ESR1), Progesterone Receptor (PGR), and/or the Human Epidermal Growth Factor Receptor-2 (HER2)." (PMID 30279965, 2018). "It is interesting to note that the mRNA levels of EIF2AK2 and ANXA1 were significantly higher while those of PGR and CCND1 were significantly lower in two ER-- breast cancer cell lines than in MCF-7 cells." (PMID 29416786, 2018). "We first examined the expression of Ki67, ER, progesterone receptor (PgR), AR, and VDR and the phosphorylation of AKT Ser473 and ERα Ser167 by immunohistochemistry (IHC) in breast cancer tissues in pre- (n = 62) and postmenopausal (n = 152) women." (PMID 29707142, 2018). "In human breast tumor tissues, mRNA levels of EIF2Ak2, USP18, DDX58, RBL2, STAT2, PGR, S1000A9, and CCND1 were significantly higher in ER+- than in ER--breast cancer tissues." (PMID 29416786, 2018). "We first aimed to stratify the RNA-Seq data available from The Cancer Genome Atlas according to the three major breast cancer subtypes: HER2-positive, ESR1/PGR-positive, and triple negative." (PMID 30279965, 2018). "Triple‐negative breast cancer (TNBC) lacks expression of estrogen receptor (ER), progesterone receptor, and the HER2 receptor; it is highly proliferative and becomes the deadliest forms of breast cancer." (PMID 29633513, 2018). "Within the subtypes of breast cancer, one stands out as highly aggressive, coupled with a triple negative histotype for estrogen receptor α (ESR1), progesterone receptor (PR) and human epidermal growth factor 2 (HER2)." (PMID 30373175, 2018). "To date, few markers like the estrogen receptor (ER), the progesterone receptor (PR) and the human epidermal growth factor receptor 2 (HER2), have been identified as predictors of clinical responses to breast cancer treatments." (PMID 30423928, 2018).
breast cancer (continued). "Overall, based on ER/PgR expression, HER2 status, and ki-67%, the number and percentages of luminal breast cancers, triple negative (TN) and HER2 enriched cases were 187 (79.5%), 30 (12.8%) and 18 (7.7%), respectively." (PMID 29769125, 2018). "In this study, we investigated the utility of a modified PEPI including the PgR status (PEPI-P) as a prognostic factor after NAE for postmenopausal patients with ER-positive and HER2-negative breast cancer." (PMID 30080878, 2018). "In general, the standard prognostic and predictive factors for breast cancer disease are human epidermal growth factor receptor 2 (HER2), progesterone receptor (PR), estrogen receptor (ER), and proliferation (Ki-67) status." (PMID 29978332, 2018). "After routine central assessment of ER, PgR, and HER2 of breast cancer patients in NCCH from January 1990 to March 2011, 740 patients were identified as TNBC." (PMID 30344939, 2018). "Taking into account the ER/PgR expression levels, recent data suggest that BC with ER expression inferior to 10% are more similar to triple-negative breast cancer (TNBC) than luminal disease, with worse survival outcomes and limited advantage from adjuvant endocrine therapy." (PMID 30261866, 2018). "In case of lncRNA HOTAIR, the RNA interacts with Polycomb Repressive Complex 2 (PRC2), affecting breast cancer progression and survival through regulation of a variety of genes such as HOXD, the progesterone receptor, and SNAIL25." (PMID 30150751, 2018). "A similar approach is also likely viable for breast cancers that overexpress other hormone receptors that activate the anticipatory UPR, such as progesterone receptor, or EGFR family members." (PMID 29963013, 2018). "Based on these thresholds, the assay can be used for the robust quantification of ERBB2, ESR1, PGR and MKI67 on whole sections of FFPE samples during routine histopathological work-up of breast carcinoma." (PMID 30342538, 2018). "By using estrogen receptor α (ER), progesterone receptor (PR), and human epidermal growth factor receptor 2 (HER2) status as a surrogate for gene expression profiling, breast cancers are commonly classified into luminal, HER2+, and triple-negative subtypes." (PMID 28698809, 2017). "For example, a patient with a grade 1, ER positive, progesterone receptor-positive, HER2-negative breast cancer has a 10-year ROR of approximately 10% to 15%; adjuvant endocrine therapy would reduce this risk by approximately one-third to one-half." (PMID 29045452, 2017). "To date, only a few markers, such as estrogen receptor (ER), progesterone receptor (PR), and human epidermal growth factor receptor 2 (HER2), have been identified as predictors of clinical responses to breast cancer treatments." (PMID 28637482, 2017). "A combination of the biomarkers ER, PgR, HER2, and Ki-67 has been used in treatment guidelines, and these entities act as surrogate markers for the molecular breast cancer subtypes." (PMID 29137653, 2017). "Hormone receptor (HR)-positive BC, which expresses ER and/or PgR, is sensitive to anti-estrogen treatment and HER2 overexpression is a predictive marker of HER2-targeted treatment in HER2-positive breast cancer." (PMID 28060723, 2017). "Pooled discordance proportion between primary and recurrent breast cancer was reported in 8% of patients with HER2, 20% of patients with ER, and 33% of patients with PgR by a meta-analysis." (PMID 28220470, 2017). "The results of the present study indicate that the low PgR (<20%) group has a markedly poorer prognosis among patients with ER-positive/HER2-negative and intermediate Ki67 LI breast cancer." (PMID 28532429, 2017). "Triple-negative breast cancer (TNBC), which lacks expression of estrogen receptor α (ERα) and progesterone receptor (PR) and human epidermal growth factor receptor 2 (HER2) gene, accounts for approximately 15% of breast cancers." (PMID 28437471, 2017).
breast cancer (continued). "Within the breast cancer data, we observe errors merging the column labeled “pr” or “pr.status” in datasets GSE11001, GSE23593 with the “progesterone receptor status” in dataset GSE36774." (PMID 28437440, 2017). "The expression of estrogen receptor (ER), progesterone receptor (PR), and human epidermal growth factor receptor 2 (HER2) play crucial roles in ductal-derived breast cancer classification, diagnose, and treatment." (PMID 28184196, 2017). "Pathological biomarkers such as estrogen receptor (ER), progesterone receptor (PgR), ErbB2, Ki‐67, cytokeratins, and epidermal growth factor (EGF) receptor are mainly used in clinical situations to define breast cancer subtypes." (PMID 28781955, 2017). "For muscle-invasive disease, the direct comparison of the breast cancer subtypes and bladder cancer subtypes has been shown and the four targeted genes ESR1, PGR, ERBB2 and MKI67 have been shown to be of diverse expression in bladder cancer." (PMID 28978063, 2017). "Canonically, breast carcinomas are grouped as luminal (luminal A and B), HER2 positive, and triple negative subtypes based on the status of estrogen receptor (ER), progesterone receptor (PR) and epidermal growth factor receptor 2 (HER2)." (PMID 28754978, 2017). "Interestingly, the 54 low amplified/equivocal breast carcinomas presented a frequency of hormonal receptor positivity significantly higher than that observed in the amplified tumors and similar to the non-amplified one (p = 0.016 for estrogen receptor and p = 0.001 for progesterone receptor)." (PMID 29029640, 2017). "The association between SIX mRNA expression with the status of estrogen receptor (ER), progesterone receptor (PR), human epidermal growth factor receptor-2 (HER2), and basal-like breast cancer was also analyzed." (PMID 27399099, 2016). "The immunohistochemical expression of the estrogen receptor (ER), progesterone receptor (PR), and human epidermal growth factor receptor-2 (HER-2) forms the platform of characterization of clinically defined breast cancer subtypes." (PMID 27483243, 2016). "Nevertheless, important drug targets in breast cancer, such as ESR1, PGR, HER2, EGFR and AR possess highly correlated in mRNA-protein expression both in tumors and cell lines." (PMID 27556158, 2016). "In the present study, we explored the cytotoxic effects of lignans 1–4 on the breast cancer cell line MCF-7, which is an ER-positive/PgR-positive luminal mammary carcinoma, endocrine responsive and often chemotherapy responsive." (PMID 27527135, 2016). "75% of basal–like breast cancers are triple negative (TNBC); i.e, they lack expression of Her2, progesterone receptor and estrogen receptors." (PMID 27283985, 2016). "For example, in breast cancer, the expression of SIRT5 had significant relation with tumor location, grade, and expression of estrogen receptor or progesterone receptor." (PMID 27990096, 2016). "Targeted therapies that rely on the expression of the estrogen receptor (ER), progesterone receptor (PgR) and epidermal growth factor receptor 2 (HER2) are effective treatments for luminal and HER2+ breast cancers." (PMID 27448975, 2016). "Breast-cancer is heterogeneous and traditionally classified according to the expression of Estrogen-Receptor-alpha (NR3A1/ERα), Progesterone-Receptor (NR3C3/PR) and/or HER2, the ERBB2 gene product." (PMID 26894976, 2016). "For example, estrogen receptor(ER), progesterone receptor (PR), and HER2 jointly define the subtypes of breast cancer." (PMID 26964035, 2016). "Betty, a 66-year-old white female, was diagnosed with stage IIB, T2N1M0, estrogen receptor/progesterone receptor–positive, HER2-negative breast cancer in 2007." (PMID 29282430, 2016).
breast cancer (continued). "As to biomarker expression levels, there were significant differences in progesterone receptor (PR) and HER2 expression levels in breast cancer tissues of different age groups." (PMID 27031236, 2016). "ER, progesterone receptor (PGR), and human epidermal growth factor receptor 2 (HER2) are important tumor markers of breast cancer, and TNBC lacks their expression." (PMID 27973439, 2016). "These important drug targets in breast cancer, ESR1, PGR, HER2, EGFR and AR have a high similarity in mRNA and protein variation in both tumors and cell lines." (PMID 27556158, 2016). "These basal type breast cancer cells of MDA-MB-231 cells and SK-BR-3 cells are known as triple-negative breast cancers for ER, progesterone receptor and erbB2 with poor prognosis." (PMID 27144558, 2016). "One of the most aggressive breast cancer subtypes is triple-negative breast cancer (TNBC), which lacks estrogen receptor (ER) and progesterone receptor (PR) expression and human epidermal growth factor receptor 2 (HER2) amplification." (PMID 26975198, 2016). "Herein, the ESR1, PGR, PRLR and GHR gene expression were analyzed and the results showed all hormone receptors to be significantly lower expressed in malignant mammary tumors compared to the group of reference tissue and benign tumors." (PMID 27649560, 2016). "From a technical perspective applying RT-qPCR for resolving the status of ERBB2, ESR1, PGR, and MKI67 represents an efficient and reproducible alternative for decentralized routine assessment of breast cancer molecular subtypes." (PMID 27389414, 2016). "The breast cancer cell line MCF-7 represents the luminal, estrogen and progesterone receptor-positive subtype whereas BT-20 cells are invasive, triple-negative breast cancer cells." (PMID 27457235, 2016). "Median of normalized gene expression of ESR1 and PGR in intact (fresh frozen n = 57; FFPE n = 83) and neutered (fresh frozen n = 11; FFPE n = 8) females with malignant mammary tumors." (PMID 27649560, 2016). "The human estrogen and progesterone receptor-positive MCF7 is a well-established and widely used model system of breast cancer cells." (PMID 27655642, 2016). "The protein expression status of estrogen receptor alpha (ER), progesterone receptor (PR), human epidermal growth factor receptor-2 (HER2) decide the group of breast cancers." (PMID 27556158, 2016). "The subtypes were designated based on the results of ER, PgR, Ki-67 and HER2 staining according to the 2013 St Gallen International Breast Cancer Conference." (PMID 25938238, 2015). "Association analyses showed that the expression of both ER (P = 0.026) and progesterone receptor (PR; P = 0.01) positively correlated with NOP14 level in breast cancers." (PMID 26213846, 2015). "Treatments for primary breast cancer as well as MBC are selected depending on the expression patterns of ER, PgR, and HER2." (PMID 26217553, 2015). "A PDX line established from a brain metastasis of a HER2-positive breast cancer showed strong membranous positivity (3+) for HER2, and weak dispersed positivity for ER and PgR, and therefore shared the same characteristics as the engrafted tumor." (PMID 25963555, 2015). "Gene expression of ERα (ESR1), PGR, PRLR, GHR and CDH-1 was detected in normal mammary tissues and in all mammary neoplasms, except in one carcinoma." (PMID 26370564, 2015). "Recently, the immunohistochemical analyses of expression of estrogen receptor (ER), progesterone receptor (PR), and human epidermal growth factor receptor 2 (HER2), are widely used to divide into 4 breast cancer subtypes (BCSs)." (PMID 26632910, 2015). "There is no bias in terms of clinical variables (estrogen receptor status, progesterone receptor status, HER2 status, patient age, Nottingham grade, or tumor size) between the included patients and the population of all eligible breast cancer diagnoses." (PMID 25722745, 2015).
breast cancer (continued). "The heterogenic background of breast cancer such as estrogen receptor (ER), progesterone receptor (PR), and human epidermal growth factor receptor (HER2), didn't seem to complicate the metabolite profile of breast cancer." (PMID 26452258, 2015). "Estrogen responsiveness was assessed by RT-PCR for known targets of estrogen receptor, including estrogen-induced growth, breast cancer (GREB) and progesterone receptor (PGR)." (PMID 26267486, 2015). "The results of the examination revealed left breast cancer (T2N1M0, stage IIB) that was positive for estrogen receptor and progesterone receptor and was HER2 3+." (PMID 25491149, 2014). "In this study, we demonstrate that progestin-activated progesterone receptor (PR) reduces GATA3 expression through regulation at the transcriptional and post-translational levels in breast cancer cells." (PMID 25479686, 2014). "Immunohistochemical (IHC) status of estrogen receptor (ER), progesterone receptor (PgR), HER2, and Ki67, has been adapted to construct molecular breast cancer subtype which can be used to make therapeutic choices." (PMID 25247558, 2014). "Alterations in ER, PgR and HER-2 expression have proven to play a major role in breast cancer progression, with ERpos and PgRpos tumors having better prognosis, while HER-2 overexpression is associated with a worse prognosis." (PMID 25495193, 2014). "She had left breast cancer (T2N1M0, stage IIB) that was positive for estrogen receptor and progesterone receptor and was human epidermal growth factor receptor type 2 3+." (PMID 25491149, 2014). "Expression of NAT1, ERα, progesterone receptor (PgR) and HER2 was analyzed in 394 breast cancer samples by immunohistochemistry." (PMID 25528056, 2014). "We analyzed mRNA and protein expression data from different breast cancer cohorts for L1CAM, estrogen receptor, progesterone receptor, Her-2 and Androgen receptor (AR) and correlated the data." (PMID 25510351, 2014). "Co-treatment of MCF7 breast cancer cells stably overexpressing miR-155 with RAD001 and E2 restored E2-induced PgR gene expression." (PMID 25283550, 2014). "Receptor status discordance, such as estrogen receptor (ER), progesterone receptor (PR) and human epidermal growth factor receptor 2 (HER2) status between primary breast cancer and metastatic lesions has been reported." (PMID 24721777, 2014). "The estrogen receptor (ER), progesterone receptor (PgR) and HER2 receptor are the only three validated biomarkers routinely applied in breast cancer management." (PMID 24670368, 2014). "One of its uses is for on-filter IHC analysis of HER2 and ER/PgR protein expression and FISH analysis of HER2 gene amplification in breast cancer cases, in addition to routine EpCAM and CD45 staining." (PMID 24523941, 2014). "CNB had good agreement in evaluating molecular subtypes as well as ER, PgR, and HER2 status in breast cancer." (PMID 23957561, 2013). "In addition, PKCα expression level correlates with estrogen receptor/progesterone receptor-negativity, higher tumor grade, increased Ki-67 positivity, and poor prognosis in human breast cancer, and the metastasis inhibitor KiSS1 may function in part by downregulating PKCα." (PMID 23613949, 2013). "Estrogen receptor (ER), progesterone receptor (PgR), HER2, and Ki67 have been increasingly evaluated by core needle biopsy (CNB) and are recommended for classifying breast cancer into molecular subtypes." (PMID 23957561, 2013). "The intrinsic subtypes of breast cancer of both ER+/PgR-/HER2- and ER+/PgR-/HER2- lead to the same luminal A type, and this immunohistochemical inconsistency does not mean genetic heterogeneity or polyclonal." (PMID 23782331, 2013). "The expression profiles of estrogen receptor (ER), progesterone receptor (PR) and human epidermal growth factor receptor (HER2)/neu have been used for predicting the outcome and response to the therapy of breast cancer for a number of years." (PMID 24260046, 2013).